NFE2L1 (NFE2 like bZIP transcription factor 1)
Diseases named in the same sentence as NFE2L1 in open-access papers (continued):
Sharing a sentence is not in itself a finding about the gene and the disease.
Blindness (1 paper, 2023). Blindness is the condition of lacking visual perception defined as a profound reduction in visual perception. "Finally, we showed that Nfe2l1 overexpression delayed visual loss in a preclinical model of human blindness caused by a misfolded protein called rhodopsin." (PMID 37450596, 2023).
colon cancer (1 paper, 2023). "However, knockout of DDI2, the protease necessary for N-terminal truncation of NFE2L1, in the human colon cancer cell line HCT116 led to a decrease in proteasome activity, suggesting that NFE2L1 may be necessary for the basal expression of proteasome subunits." (PMID 37759569, 2023).
COVID-19 (1 paper, 2023). A disease caused by infection with severe acute respiratory syndrome coronavirus 2. "Nuclear factor erythroid-2 like 1 (NFE2L1) and glutathione peroxidase 3, which regulate oxidative stress and inflammatory responses, were upregulated following COVID-19 (P < 0.001 and P = 0.010, respectively)." (PMID 37019821, 2023).
Crohn disease (1 paper, 2023). A gastrointestinal disorder characterized by chronic inflammation involving all layers of the intestinal wall, noncaseating granulomas affecting the intestinal wall and regional lymph nodes, and transmural fibrosis. "Although there are a limited number of studies that explore NFE2L1 expression as a direct cause of Crohn’s disease, its typical genetic association and functional significance in other IBDs suggest that it may play an important role." (PMID 38069122, 2023).
diabetic nephropathy (1 paper, 2023). "The mean expression of NFE2L1 was slightly higher in diabetic nephropathy and mesangial IgA cases compared to other renal diseases." (PMID 37681897, 2023).
glioma (1 paper, 2025). A benign or malignant brain and spinal cord tumor that arises from glial cells (astrocytes, oligodendrocytes, ependymal cells). "Further investigations revealed that among the immune‐infiltrating cell types in glioma, NFE2L1 displayed the strongest association with macrophage infiltration." (PMID 40677211, 2025). "We demonstrated NFE2L1's role in macrophage polarization affecting glioma cells, showing that NFE2L1‐deficient macrophages inhibit glioma cell migration, aligning with research on targeting macrophage polarization to stop tumor progression." (PMID 40677211, 2025). "Histological analysis through hematoxylin and eosin (HE) staining, accompanied by Ki67 proliferation assays, revealed that tumor growth and cellular proliferation were markedly inhibited in C57BL/6 mice with NFE2L1 deficiency following the implantation of GL261 glioma cells." (PMID 40677211, 2025). "Deficiency of NFE2L1 causes a unique phenotypic switch in the TAMs from its pro‐cancer M2‐type to another anti‐cancer M1‐type, thereby inhibiting malignant progression of glioma." (PMID 40677211, 2025). "In the present investigation, we explored the regulatory role of NFE2L1 in the phenotypic polarization of TAMs and the proliferation of glioma cells." (PMID 40677211, 2025). "Given the pivotal role of epithelial–mesenchymal transition (EMT) in the invasion and metastasis of glioma, we treated LN229 and U251 cells with CM from NFE2L1‐deficient macrophages." (PMID 40677211, 2025). "Thereby, we here explore the impact of such a key regulatory transcription factor NFE2L1 (also called Nrf1) on glioma‐relevant TAMs." (PMID 40677211, 2025). "In conclusion, our research reveals NFE2L1's role in regulating TAMs in glioma, suggesting it as a therapeutic target." (PMID 40677211, 2025). "Such NFE2L1‐deficiency leads to significantly increases of CD8+ T cells and M1 macrophages within tumor tissues of glioma and hence enhances its sensitivity to anti‐PD1 therapy." (PMID 40677211, 2025). "Our findings indicated that NFE2L1 is predominantly expressed in glioma tumor tissues, with NFE2L2 exhibiting lower expression levels, whereas NFE2L3 was expressed at minimal levels." (PMID 40677211, 2025). "Validation through RT–qPCR and immunoblotting further confirmed the upregulation of NFE2L1 in glioma tumors relative to normal brain tissue." (PMID 40677211, 2025). "Research indicates that modulating NFE2L1 expression can stimulate the Wnt signaling pathway, subsequently influencing glioma cell proliferation." (PMID 40677211, 2025). "Our study found that NFE2L1 is upregulated in glioma patients, highlighting its key role in malignancy progression." (PMID 40677211, 2025). "Our findings indicate that the downregulation of NFE2L1 facilitates a transition of TAMs from the M2 phenotype to the M1 phenotype, which in turn hinders the aggressive proliferation of glioma." (PMID 40677211, 2025). "The aberrant role of NFE2L1 in the malignant progression of glioma was discovered in this study." (PMID 40677211, 2025). "Acknowledging the potential role of NFE2L1 in the malignant progression of glioma, we hypothesized that NFE2L1 could facilitate glioma development in vivo." (PMID 40677211, 2025). "In our subsequent analysis, we sought to determine whether variations in NFE2L1 expression are correlated with shifts in the immune microenvironment of glioma tumors." (PMID 40677211, 2025). "Importantly, our study shows that inhibiting NFE2L1 boosts anti‐PD1 immunotherapy effectiveness in glioma, suggesting it as a valuable therapeutic target for enhancing TAMs and antitumor responses." (PMID 40677211, 2025). "High‐expressed NFE2L1 contributes to maintaining the M2 macrophage in glioma." (PMID 40677211, 2025). "We focused on elucidating the function of NFE2L1 within the context of glioma." (PMID 40677211, 2025).
glioma (continued). "To investigate the role of NFE2L1 in the glioma microenvironment, we initially established a single‐cell transcriptional atlas derived from tumors of glioma patients, focusing on the expression profiles of the nuclear factor erythrocyte 2‐like (Nfe2l) gene family." (PMID 40677211, 2025). "Our study further investigates the role of NFE2L1 in gliomas by clarifying the intricate relationship between its expression and the polarization of TAMs within the glioma microenvironment, thereby underscoring the potential of NFE2L1 as a viable therapeutic target for glioma treatment." (PMID 40677211, 2025). "Based on these results, NFE2L1 may play a significant role in the TAMs of glioma." (PMID 40677211, 2025). "To delve deeper into the potential impact of NFE2L1 expression in macrophages on the functionality of glioma cells, we engineered THP‐1 cells with a targeted knockout of NFE2L1." (PMID 40677211, 2025). "However, NFE2L1 shapes the tumor immune microenvironment, but its relationship with CD38 needs clarification, indicating potential for glioma therapy." (PMID 40677211, 2025).
glomerular disease (1 paper, 2023). "The nuclear expression of NFE2L1 in podocytes was found to be reduced by up to 3-fold in biopsies of patients with glomerular disease." (PMID 37681897, 2023). "Therefore, we postulate that lipid accumulation and the effect on NFE2L1 expression in podocytes are contributory factors in the pathogenesis of glomerulopathies; however, further work is required to elucidate the role of cholesterol metabolism and NFE2L1 in the context of podocyte injury." (PMID 37681897, 2023). "We evaluated the podocyte expression of NFE2L1, Nuclear Factor Erythroid 2-related Factor 2 (NFE2L2), and NAD(P)H:quinone Oxidoreductase (NQO1) in 127 human glomerular disease biopsies using multiplexed immunofluorescence and image analysis." (PMID 37681897, 2023).
liver disease (1 paper, 2025). "As shown in the heat map, male offspring exposed to HSD exhibited differential expression of ten genes associated with liver disease compared to normal offspring: Ager, Dph1, Steap4, Nfe2l1, Ppara, Rbmx, Nr1d1, Ccar2, Axl, and Abcg5." (PMID 41036197, 2025).
lung carcinoma (1 paper, 2024). "The effects of taurine on lung cancer progression vary depending on immune competence, with Nfe2l1 exhibiting anti-tumor properties." (PMID 39867697, 2024).
malignant glioma (1 paper, 2025). A grade III or grade IV glioma arising from the central nervous system. "Notably, the expression of NFE2L1 was significantly elevated in malignant glioma cells and Mono/Macrophages compared with that of NFE2L2 and NFE2L3." (PMID 40677211, 2025).
melanoma (1 paper, 2016). A malignant, usually aggressive tumor composed of atypical, neoplastic melanocytes. "Thus, GCLC and NFE2L1 upregulation in A7 may contribute to both the increased ROS scavenging capacity compared with G10 and controls and its more differentiated and less aggressive melanoma." (PMID 27206673, 2016).
metastatic tumor (1 paper, 2020). "The results showed that the expression of NFE2L1 in metastatic tumor was lower than that in the primary tumor (p value < 0.05) in the GSE22541 dataset." (PMID 32316228, 2020). "In addition, the expression of NFE2L1 and MTFR1L in metastatic tumor samples is lower than that in primary tumor samples." (PMID 32316228, 2020).
minimal-change disease (1 paper, 2023). "Interestingly, even in cases of minimal-change disease (MCD), which is known to cause podocyte effacement, nuclear NFE2L1 expression was significantly decreased." (PMID 37681897, 2023).
osteosarcoma (1 paper, 2024). A usually aggressive malignant bone-forming mesenchymal neoplasm, predominantly affecting adolescents and young adults. "Second, chromatin immunoprecipitation assays demonstrate that NFE2L1 binds the genes GCLC, FTH1, ABCC1, FTL, HMOX1, and AIFM2/FSP1 in osteosarcoma cells." (PMID 39025451, 2024). "This may not be universal as NFE2L1 can bind the GPX4 promoter in osteosarcoma cells." (PMID 39025451, 2024).
ovarian carcinoma (1 paper, 2024). A malignant neoplasm originating from the surface ovarian epithelium. "In ovarian cancer, higher NFE2L1 levels were associated with shorter progression-free survival, and NFE2L1 was positively correlated with CD8+ T cell, macrophage, and neutrophil infiltration." (PMID 39061827, 2024). "Gene set enrichment analysis and prognosis analysis indicated that NFE2L1 could be a key transcription factor in the acquisition of metastasis potential in ovarian cancer cells." (PMID 39061827, 2024).
pancreatic endocrine tumors (1 paper, 2022). "Silencing of NFE2L1 induced aggressiveness and chemoresistance in pancreatic endocrine tumors, indicating a tumor-suppressive role of NFE2L1." (PMID 35059466, 2022).
preeclampsia (1 paper, 2015). Preeclampsia is a hypertensive disorder of pregnancy that is characterized by new-onset hypertension with proteinuria presenting after 20 weeks of gestation, and depending on mild or severe forms may initially present with severe headache, visual disturbances, and hyperreflexia. "RT-qPCR confirmed aberrant expression of genes involved in inflammation and stress response (TLR4 and TLR9) and also genes involved in host defense (PRDX5, MIF, CD74, NFE2L1, and CSF3R), suggesting that preeclampsia sera suppress the TLR4/9-dependent excess oxidative stress in adipose tissue." (PMID 26089598, 2015).
retinal degeneration (1 paper, 2023). Degeneration of the retina. "Therefore, the type of proteotoxic stress and form of retinal degeneration may affect the efficiency of Nfe2l1 activation, particularly mediated via chronic stimulation of mTORC1 pathway." (PMID 37450596, 2023).
thyroid cancer (1 paper, 2019). "The increased expression of MAP2K1 is due to the positive regulation of NFE2L1 with phosphorylation, which could promote the progression of the tumor cell cycle and increase the growth and proliferation of thyroid cancer cells." (PMID 31126066, 2019).
cancer (25 papers, 2015 to 2026). A tumor composed of atypical neoplastic, often pleomorphic cells that invade other tissues. "The NFE2L1 (also referred to as NRF1) protein has been implicated in cancer development, and degenerative, and metabolic disorders." (PMID 32316228, 2020). "CD151 is involved in cancer progression and neovascularization, and its overexpression is upregulated by NFE2L1 and influenced by DNA methylation to cause a high migration ability of cancer cells in early-stage PTC." (PMID 31126066, 2019). "Therefore, this review will provide a summary of the role of NFE2L1 in cancer and the underlying molecular mechanisms from the perspective of hallmarks of cancer." (PMID 39061827, 2024). "Furthermore, NFE2L1 levels are altered in a variety of cancers and are associated with the malignancy of several cancers." (PMID 39061827, 2024). "The interaction between PD‐1 on T cells and PD‐L1 on tumor cells impedes the cancer immunity cycle, suggesting a model where inhibition of NFE2L1 leads to immune activation and a shift of the TME toward a more inflammatory state." (PMID 40677211, 2025). "Zhang’s group made a series of attempts to interpret the role of NFE2L1 in cancer cell proliferation." (PMID 39061827, 2024). "Recently, NFE2L1-related isoforms and SNPs serve as potential therapeutical targets for neurodegenerative diseases and cancer, and are receiving increased attention." (PMID 39061827, 2024). "Here, we have organized an interaction diagram between NFE2L1 and hallmarks to facilitate understanding of the research progress of NFE2L1 in cancers." (PMID 39061827, 2024). "Recent studies have shown that NFE2L1 mediates cell proliferation and metabolic reprogramming in various cancer cell lines." (PMID 39061827, 2024). "These ongoing efforts aim to contribute to the development of potential novel cancer therapies that target the NFE2L1 pathway and its activity." (PMID 39061827, 2024). "We combined the framework provided by “hallmarks of cancer” with recent research on NFE2L1 to summarize the role and mechanism of NFE2L1 in cancer." (PMID 39061827, 2024). "Several studies have shown that NFE2L1 plays the role of inhibiting inflammation response only in cancer cell line and immune cell line models." (PMID 39061827, 2024). "Accumulating studies demonstrate that NFE2L1 is also crucial for metabolic reprogramming in various cancers." (PMID 39061827, 2024). "This review presents evidence of the tumor-suppressing and tumor-promoting effects of NFE2L1 according to its roles in nine hallmarks of cancer." (PMID 39061827, 2024). "More and more studies have confirmed that NFE2L1-mediated downstream regulatory genes play an important role in regulating redox homeostasis, as well as in cancer cells." (PMID 39061827, 2024). "In summary, NFE2L1 in cancer cells plays an important role in resisting cell death, including apoptosis, pyroptosis, and ferroptosis." (PMID 39061827, 2024). "For example, upregulation of 41BBL by NFE2L1 facilitated cancer cell senescence and the production of ROS, inhabiting the growth of cancer cells." (PMID 38851002, 2024). "The activation of transcription factor Nuclear factor erythroid 2 related factor-1 (NFE2L1) has been characterized as a potential resistance response to protect and restore proteasome activity in cancer cells." (PMID 37298331, 2023). "Although the function of NFE2L1/2 and its binding partners (MafG, MafF, and MafK) to form heterodimers in cancer has been extensively studied, their distinguishing roles in the regulation of PD-L1 and immune evasion are poorly understood." (PMID 37985752, 2023). "Recently, Nuclear factor erythroid 2-related factor-1 (NFE2L1) has been identified as a protein involved in PI resistance in cancer cells." (PMID 37298331, 2023). "NFE2L1 is a critical proteasome regulator in cancer cells for the maintenance of their basal proteasome activities via activating proteasome-related genes, and NFE2L1 knock-out mice suffered embryonic lethality." (PMID 35059466, 2022).
cancer (continued). "Multifaceted roles of NFE2L1 in cellular homeostasis have been reviewed recently, but the current understanding of its pathological involvement in cancer development is limited." (PMID 32942643, 2020). "From this analysis, 10 commonly regulated genes were identified, and we validated the role of four genes (ENO2, EphB2, SerpinE1, and STX12), which were reportedly involved in cancer cell activities, as downstream targets of NFE2L1." (PMID 32942643, 2020). "It is important to point out that this is the first time that STAT2, NFE2L1, SIN3B and NOTCH2 genes are described associated to the cancer stroma." (PMID 31159827, 2019). "RAP2C is overexpressed by TF NFE2L1 inducing cancer cell migration and invasiveness ability, it also has a higher basal level in early-stage PTC cells compared with normal thyroid cells, causing DNA methylation promoting gene activity and cell migration." (PMID 31126066, 2019). "However, cancer cells counteract this effect by activating an adaptive response through the transcription factor nuclear factor erythroid 2-related factor 1 (NRF1, also known as NFE2L1)." (PMID 42115609, 2026). "Interfering with proteasome function and preventing NFE2L1 activation at the same time might further sensitize cancer cells to ferroptosis." (PMID 39384955, 2025). "Therefore, the strategy of NFE2L1 activity inhibition has been used to sensitize the resistance of proteasome inhibitor treatments in cancers." (PMID 39061827, 2024). "As a transcription factor, NFE2L1 undoubtedly plays an important role in various cancers." (PMID 39061827, 2024). "Besides proteasome inhibitor cancer therapy, NFE2L1 also regulates other types of chemotherapy-induced regulated cell death (RCD), including apoptosis, ferroptosis, and genotoxic stress-induced cell death." (PMID 39061827, 2024). "However, long-isoform NFE2L1 promotes cancer invasion and metastasis under chronic stress conditions." (PMID 39061827, 2024). "NFE2L1 plays a huge role in the metabolic reprogramming of cancers." (PMID 39061827, 2024). "The ratio of the NFE2L1 isoforms is dependent on the cell types and altered in cancers." (PMID 39061827, 2024). "Whether NFE2L1 inhibits cancers in all cancers or whether the role played by NFE2L1 depends on the type and stage of the cancer, as in NRF2, is still uncertain." (PMID 39061827, 2024). "Over the past decade, studies have found NFE2L1 is involved in the regulation of key processes related to the hallmarks of cancer, including tumor growth, invasion, migration and metastasis, cell death, genomic instability, reprogramming cell metabolism, inflammation, and cell senescence." (PMID 39061827, 2024). "The value of NFE2L1 for developing precise cancer treatment is immeasurable." (PMID 39061827, 2024). "It was reported that ROCK1 and NFE2L1 could activate the activity of Wnt signaling pathway in human cancers." (PMID 34536977, 2021). "Besides glucose and amino acid metabolism, NFE2L1 also regulates lipid metabolism in cancer." (PMID 39061827, 2024). "Therefore, this study suggests that NAT10 may exert a pro-cancer effect by modulating the nuclear factor erythroid-2, like-1(NFE2L1)-glutathione peroxidase-4(GPX4)signaling pathway in ccRCC, indicating its potential as a new therapeutic target for this malignancy." (PMID 41189569, 2025). "Taken together, our results demonstrate the critical role of locus 22, NFE2L1, and MAFG in helping cancer cells evade T-cell killing by upregulating super-enhancer–mediated PD-L1 expression." (PMID 37985752, 2023). "To further support these conclusions, we analyzed the cancer cell line database across all members of the NFE2:MAF family including MAFG, MAFF, MAFK, NFE2L1, and NFE2L2." (PMID 37985752, 2023). "NFE2L1 and its paralog NFE2L3 maintain the basal proteasome activity, while the simultaneous deletion of those proteins impairs proteasome function in cancer." (PMID 37662900, 2023).
cancer (continued). "In this study, we therefore explored the relevance of the paralogous NFE2L1 in NSCLC, given that it has not previously been studied in this cancer type." (PMID 38562019, 2024).